KRAS (KRas proto-oncogene, GTPase)
Diseases named in the same sentence as KRAS in open-access papers (continued):
Sharing a sentence is not in itself a finding about the gene and the disease.
lung cancer (continued). "KRAS (Kirsten rat sarcoma viral oncogene homolog) stimulates the Fos-mediated transcriptional activity of YAP in a mouse model of lung cancer and activates the expression of genes involved in the EMT process." (PMID 32164350, 2020). "Here, we found that, in mutant KRAS and in a subset of wild-type KRAS lung cancer cells, high prostaglandin levels are sustained by LPIAT1 activity and depend on the ACSL3-activated AA substrate availability." (PMID 32034305, 2020). "Similar to pancreas, bladder, colorectal, and lung cancer cell lines with RAS mutations, KRAS-mutant MDA-MB-231 breast cancer cells were robustly macropinocytic in complete medium." (PMID 32111826, 2020). "Preclinical studies have suggested combinations of mTOR and MEK inhibitors in KRAS mutant lung cancers but these attempts have proven challenging due to adverse events such as diarrhea, skin rash and fatigue." (PMID 32560574, 2020). "Co-occurrence of mutation in AGTPBP1 and other altered biomarkers EGFR, KRAS, BRAF, ALK and ROS1 in lung cancer was analyzed." (PMID 33276627, 2020). "The requirement for NF-κB has been also evident in lung cancer, which also presented NF-κB and IKKβ as potential therapeutic targets in KRAS-induced tumours." (PMID 33116132, 2020). "Taken together these data highlight a correlation between cyclin D1/CDK4 expression and KRAS mutation in lung ADC, suggesting enhanced activation of CDK4/Cyclin D in KRAS mutant lung cancer." (PMID 32104498, 2020). "Intervention of PIERCE and AKT in ER stress-induced TRIB3 expression shows that PIERCE1 modulates AKT phosphorylation in mutant KRAS-driven lung cancer." (PMID 32728173, 2020). "Advances in DNA sequencing technology revealed the driver mutations in lung cancers at the genes including EGFR, ROS1, BRAF, ALK, and KRAS." (PMID 33276627, 2020). "Systemic inhibition of MYC by OmoMYC in KRAS-driven lung cancer, in MYC-induced papillomatosis and in glioma was also shown to have a profound therapeutic effects, and yet only elicited mild and rapidly reversible side effects on normal tissues." (PMID 31636382, 2020). "The authors reported that silencing DGKη in lung cancer models, characterized by EGFR and KRAS mutations, reduced cancer cell growth while enhancing the cells’ sensitivity to EGFR inhibitor Afatinib." (PMID 32722576, 2020). "Kirsten rat sarcoma viral oncogene homolog (KRAS) is one of the most common mutant oncogenes in non‐small cell lung cancer (NSCLC)." (PMID 33022831, 2020). "While KRAS activates NF-κB, NF-κB strongly contributes to the oncogenic effects of KRAS in lung cancer." (PMID 32545208, 2020). "At the 2019th World Conference of Lung Cancer, the KRAS G12C-specific inhibitor AMG510 showed promising results in the phase I clinical trial." (PMID 32607238, 2020). "PIERCE1 depletion successfully suppressed tumor cell growth and decreased AKT phosphorylation, specifically in KRAS-mutant lung cancer cells." (PMID 32728173, 2020). "We next sought to explore our findings in the context of mutant EGFR lung cancers, which possess an immunosuppressive microenvironment but present with low levels of PD-L1 compared to KRAS mutant lung cancers." (PMID 32908154, 2020). "Our results validate our screening paradigm for in vitro testing of novel rexinoids and demonstrate the potential for MSU-42011 to be developed for the treatment of KRAS-driven lung cancer." (PMID 33335263, 2020). "For this investigation, PIERCE1 KO mice were crossed with KRASLA2 mice to generate mutant KRAS-induced spontaneous lung cancers." (PMID 32728173, 2020). "Whilst we are not aware of any data that interrogates pathway reactivation upon BRAF inhibition in BRAF mutant lung cancer models, pathway reactivation after KRAS G12C inhibition in G12C mutant lung cancer has been analysed." (PMID 32922659, 2020). "AKT plays important roles in mutant KRAS-driven cancers and the increased expression pattern of PIERCE1 has been detected in patients with KRAS-mutant type lung cancers." (PMID 32728173, 2020).
lung cancer (continued). "Instead of gossypol treatment, the combination of the loss of ALDH1L1 deletion and phenformin treatment decreased tumor growth in an in vivo KRAS-driven lung cancer model, and the synergy correlated with a decrease in ATP production." (PMID 32883024, 2020). "KRAS is a known oncogene and has been heavily shown in the literature to be involved with lung cancer induced by space radiation." (PMID 32045996, 2020). "As more and more targets such as KRAS become clinically actionable, the landscape of lung cancer therapeutic management will continue to change." (PMID 32549358, 2020). "Data analysis reveal that KRAS overexpression in CAF medium enhanced the sphere-propagating capacity in lung cancer cells, in comparison with NF of CAF alone groups." (PMID 32754302, 2020). "Deletion of EGFR in a mouse model of autochthonous lung cancer driven by KRASG12D reduced KRAS activity and transiently retarded tumor growth." (PMID 32560574, 2020). "The PD-1/PD-L1 pathway has been heavily targeted as a treatment for cancer, with several inhibitors approved by the FDA for the treatment of KRAS-driven cancers, including colon and lung cancers." (PMID 33396954, 2020). "Genetic alterations in MAPK/ERK pathway are very common in non‐small cell lung cancer (NSCLC), especially mutations found in the upstream members, EGFR and KRAS, which account for 70% or more of all known driver mutations." (PMID 32757330, 2020). "KRAS-mutant lung cancer cells are refractory to 1,25(OH)2D3 due to perturbations in key determinants of vitamin D signaling, such as low levels of VDR and elevated expression of CYP24A1." (PMID 32183160, 2020). "Another drug, MRTX849, has also shown potent efficacy in vitro and in vivo for G12C positive lung cancer, with pronounced tumor regression in 17 of 26 (65%) KRAS G12C positive cell lines." (PMID 32549358, 2020). "This sequence of events has been shown in lung cancer where hypermethylation of PRC2 target genes sensitizes epithelial cells to single-step transformation by mutant KRAS." (PMID 31807902, 2020). "Through the STAT3 pathway, IL-22 which is secreted by CD4+ αβ and γδ T cells, stimulates oncogenic KRAS-driven lung cancer development by promoting a pro-inflammatory microenvironment." (PMID 33116132, 2020). "To set up a cellular system for this, we first tested ferroptosis sensitivity of a panel of KRAS-mutant lung cancer cell lines in response to erastin, which has been shown to inhibit xCT, thereby inducing ferroptosis." (PMID 33050207, 2020). "KRAS-mutant non-small cell lung cancer (NSCLC) is a major lung cancer subtype that leads to many cancer-related deaths worldwide." (PMID 32728173, 2020). "This notion is also supported by a clear co-occurrence with STK11 and KRAS gene alterations with a suggested synergic role of these genes in enhancement of tumorigenesis and lung cancer progression." (PMID 32971994, 2020). "Typical for pancreatic, colorectal, and lung cancer are KRAS alterations, whereas HRAS is more specific to melanoma and head and neck cancer, followed by NRAS in hematological malignancies." (PMID 32545208, 2020). "Research has uncovered a role for CCL5 in KRAS-induced lung cancer, where it is involved in a cytokine circuit along with IL-6 and STAT3 driving tumorigenesis." (PMID 33116132, 2020). "Currently, limited information is available concerning the changes in DMEs in patients with KRAS mutant lung cancer." (PMID 33240601, 2020).
lung cancer (continued). "A large scale phase III clinical trial (Galaxy-2) in advanced lung cancer evaluated the effects of combining ganetespib and anti-microtubule agent docetaxel in either KRAS mutant or KRAS wild type non-small cell lung cancer (NSCLC) patients." (PMID 32766157, 2020). "Our study involved several lung cancer models including H1975 (EGFR mutations), A549 (KRAS mutation), and H1299 (NRAS mutation)." (PMID 33214553, 2020). "KRAS mutant lung cancers have worse outcomes in both early stage and advanced metastatic settings, illustrating the critical need for novel agents targeting KRAS-driven NSCLC." (PMID 32560574, 2020). "For these experiments, we used immortalized bronchial epithelial cells (3KT), wild-type (H2126), and mutant-KRAS (H1792) lung cancer cells." (PMID 31874105, 2020). "In 1973, a murine sarcoma virus transformed mammalian genes into an oncogene in KRAS, and nearly a decade later, a human lung carcinoma cell line first showed human sequences analogous to the KRAS oncogenes in mice." (PMID 32560187, 2020). "Silencing REG4 reduced cancer cell proliferation and tumorigenesis in vivo and in vitro by blocking G2/M transition, suggesting an important role of REG4 in KRAS-driven lung cancer pathogenesis." (PMID 33489872, 2020). "Preclinical studies in mouse models of KRAS-mutant lung cancer suggest that harmine, a β-carboline alkaloid, can be used to target TWIST1 with high efficacy." (PMID 30909364, 2019). "For example, patients that present with mutant KRAS nonsmall cell lung cancer have been well documented to be unresponsive to EGFR tyrosine kinase Inhibitor (TKI) therapy." (PMID 30941175, 2019). "KRA-553-induced hyperactivation of mutant KRAS facilitates apoptotic and autophagic cell death in mutant KRAS lung cancer cells." (PMID 30971271, 2019). "Although this issue is outside the scope of the present study, it is possible that the mutant KRAS-actuated phenotypic switch we observe with lung cancer-derived exosomes is transient and the number of T cells converted would depend on the tumor mass." (PMID 31635338, 2019). "A xenograft mice model of lung cancer harboring KRAS mutant was established by using KRAS(G12V) H441 cells." (PMID 31484165, 2019). "In KRAS-mutant lung cancer, tumors carrying KRASG12C exhibited higher ERK1/2 phosphorylation than those with KRASG12D." (PMID 31612108, 2019). "Cell apoptosis assays were performed with single inhibitor or a combination of AZ628 and BP-1-102 on a panel of KRAS mutant lung cancer cells and wild-type lung cancer cells." (PMID 31484165, 2019). "Activated BACH1 increases the transactivation of glycolysis genes such as Hexokinase 2 and Gapdh which stimulates the KRAS-driven lung cancer metastasis." (PMID 31884422, 2019). "Toward repurposing drugs for CSC inhibition, we initially screened an NCI Diversity library of FDA-approved drugs using H460 human lung cancer cell line which contains mutations in the clinically relevant genes EGFR and KRAS." (PMID 31796785, 2019). "In another KRAS-driven lung cancer mouse model, depletion of Gr-1+CD11b+ myeloid cells also suppressed tumor growth." (PMID 31847096, 2019). "For instance, the administration of such vaccines enhances antigen-specific cytotoxic T lymphocyte responses in vitro and in vivo, resulting in antitumor effects against KRAS-driven pancreatic and lung cancers." (PMID 31438559, 2019). "Among them, MAPK signaling plays an important role in KRAS mutant lung cancer, and the components of this pathway have been widely used to develop drugs for KRAS inhibition." (PMID 31484165, 2019). "To confirm the synergistic effect of RAF and STAT3 inhibitors, we evaluated their roles in the growth of KRAS mutant lung cancer cells by using AZ628 (2 μM) and BP-1-102 (10 μM)." (PMID 31484165, 2019).
lung cancer (continued). "Currently, the platinum-based chemotherapy is still widely used for patients with KRAS-mutant lung cancer." (PMID 31612108, 2019). "The combination showed a strongly synergistic interaction in KRAS-mutant lung cancer cells compared with wild-type cancer cells, and KRAS-mutant lung cancer cells were more sensitive to this combination than AZ628 or BP-1-102 single." (PMID 31484165, 2019). "Further, the MYC expression is positively associated with AXL, EIF4E, and EMT signatures and both mRNA and protein levels of the EIF4E are of prognostic significance in KRAS-mutant lung cancer, lung adenocarcinoma, and lung cancer." (PMID 31431614, 2019). "For example, KRAS-mutant lung cancer and pancreatic ductal adenocarcinoma cells showed resistance to MEK inhibitors and mTOR inhibitors, respectively." (PMID 31214504, 2019). "In this study, we investigated the molecular mechanisms underlying adaptive resistance to currently available cancer drugs in KRAS-mutant lung cancer." (PMID 31431614, 2019). "Since A549 cells harbor a mutant KRASG12S allele, we next explored how a TTF-1 transgene would impact the cisplatin sensitivity of another KRAS mutant-containing lung cancer cell line (NCI-H460, KRASQ61H)." (PMID 31142791, 2019). "KRAS mutations are common genetic alterations in NSCLC and contribute to the resistance of lung cancer to conventional therapy." (PMID 30971271, 2019). "KRAS mutation in endometrial cancer and NF1 mutation in lung cancer case were annotated resistance information only in the OKR system." (PMID 31383922, 2019). "The importance of RALB and TBK1 to RAS-induced lung cancer was confirmed in a RNA inhibitor screen of synthetic lethal partners of oncogenic KRAS, where RALB and TBK1 were identified as top targets." (PMID 31681587, 2019). "These preclinical studies provide new insights into KRAS-driven tumorigenesis and bring new hope for KRAS-mutant lung cancer patients." (PMID 31612108, 2019). "With respect to lung cancer, EGFR mutations are present in 14% of all LAC patients, and are mutually exclusive with KRAS mutations." (PMID 31438559, 2019). "The let-7 family was able to repress KRAS and slow the proliferation of lung cancer cells both in vitro and in mouse models." (PMID 30935143, 2019). "Collectively, these results uncover collateral vulnerabilities co-occurring with drug resistance and tumor heterogeneity, informing novel therapeutic avenues for KRAS-mutant lung cancer." (PMID 31431614, 2019). "We focused on five important and clinically actionable gene targets (EGFR (Exon 19 deletions, L858, and T790), BRAF (V600), and KRAS (G12/G13)), whose alterations are particularly relevant to lung cancer, melanoma, and colorectal cancer." (PMID 31581267, 2019). "In this study, we characterized the combination therapy of AZ628, the inhibitor of RAF, and BP-1-102, the inhibitor of STAT3, in KRAS mutant lung cancer." (PMID 31484165, 2019). "Aside from impacting the immune contexture of lung cancers, mutant KRAS contributes towards an immune-suppressive microenvironment in CRC, allowing the escape to immune recognition." (PMID 31847096, 2019). "KRA-533 exhibited potent antitumor activity against mutant KRAS lung cancer via induction of KRAS hyperactivation, apoptosis and autophagic cell death in NSCLC xenografts." (PMID 30971271, 2019). "NF1 encodes for a negative regulator of KRAS and inactivation leads to EGFR inhibitor resistance in lung cancer." (PMID 31287991, 2019). "Inhibition of mutant KRAS activity, cell growth, and tumour dissemination by deltarasin has been reported in pancreatic cancer, lung cancer and colon cancer." (PMID 30833665, 2019). "Nanoliposomes can also be used to deliver miRNAs that specifically target KRAS and impair tumor growth and metastasis in lung cancer models." (PMID 31681559, 2019). "We recently found that activation of mTOR signaling mediates a key resistance mechanism to chemotherapy in KRAS-mutant lung cancer." (PMID 31612108, 2019).
lung cancer (continued). "In line with these mechanistic findings, HSP90 inhibitors synergistically enhance antitumor effects of pemetrexed and MEK inhibitors in multiple in vitro and in vivo models, validating a rational combination strategy to treat KRAS-mutant lung cancer." (PMID 31612108, 2019). "Mechanistically, in mesenchymal-like KRAS-mutant lung cancer cells, ZEB1 directly represses IL17RD to mediate the resistance to MEK inhibitors." (PMID 31612108, 2019). "In KRAS-driven lung cancer, it has been indicated that the inhibition of FADD phosphorylation suppresses tumor development, suggesting that FADD kinase is a plausible therapeutic target." (PMID 31569512, 2019). "In lung cancer models, KRAS supports expression of IL6-mediated chronic inflammation, which reorganizes the tumor microenvironment by recruiting myeloid derived suppressor cells." (PMID 31681559, 2019). "Another important oncogene in lung cancer is the KRAS (Kirsten rat sarcoma viral oncogene homolog), which codifies an EGFR downstream GTPase20." (PMID 30824880, 2019). "KRAS activation can activate inflammatory processes in lung cancer models by stimulating accumulation of macrophages and neutrophils through production of inflammatory chemokines." (PMID 31681559, 2019). "KRAS mutant lung adenocarcinoma cancer shows a poor prognosis compared with other solid tumors and molecular subtypes of lung cancer due in part to the progress of resistance to currently systemic or targeted therapy." (PMID 31484165, 2019). "The results showed that single inhibitor also owned the ability to induce cell apoptosis in both KRAS mutant lung cancer cells and wild-type lung cancer cells." (PMID 31484165, 2019). "Two SASP components, TNF-α and ICAM-I, were critically required for promoting NK cell surveillance of the drug-treated tumour cells, tumour regression and prolonged survival in the KRAS-mutant lung cancer model." (PMID 30626155, 2019). "Treatment of human lung cancer cells with KRA-533 resulted in increased KRAS activity and suppression of cell growth." (PMID 30971271, 2019). "Our finding that HSP90/AXL/eIF4E-regulated UPR fosters tumor evolution and heterogeneity provides a conceptual framework for developing rational therapeutic strategies to treat KRAS-mutant lung cancer." (PMID 31431614, 2019). "Although different KRAS mutations show a preference for activating different downstream signaling, hyperactivation of the mitogen-activated protein kinase (MAPK) pathway is generally recognized as a key feature in KRAS-driven lung cancer cells." (PMID 31612108, 2019). "We used a variety of experimental approaches to demonstrate that mutant KRAS TDEs from lung cancer cell lines, patient serum, and xenograft mice can actuate phenotypic switching in T cells independent of cytokines produced by the tumor cells." (PMID 31635338, 2019). "KRAS is a driver of many highly aggressive human malignancies including pancreatic, colon, and lung cancers." (PMID 31712554, 2019). "Our study shows that TTF-1 sensitizes the KRAS-mutated A549 and NCI-H460 lung cancer cells to cisplatin, a common chemotherapy used to treat lung cancer." (PMID 31142791, 2019). "This was validated using a mouse model of lung cancer, supporting a role for mutant KRAS on the regulation of Tregs infiltration in different types of cancer." (PMID 31847096, 2019).